OTUD1 (OTU deubiquitinase 1)
Description:
Deubiquitinating enzyme that specifically hydrolyzes 'Lys-63'-linked polyubiquitin to monoubiquitin. Required for the stability and translation of a subset mRNAs with a high abundance of rare codons by mediating deubiquitination of 40S ribosomal protein RPS10/eS10, thereby antagonizing ZNF598-mediated 40S ubiquitination. The abundance of rare codons in mRNAs can limit the translation rate and can lead to ribosome collisions that trigger activation of ribosome quality control (RQC) pathway by ZNF598. OTUD1-mediated deubiquitination prevents activation of the RQC and subsequent dissociation of ribosomes and stimulates formation of polysomes and translation.
Synonyms: DUBA7; OTDC1
Tractability: PROTAC: ubiquitination databases record sites on it.
Target class: Enzyme; Hydrolase
Gene: Protein-coding gene on chromosome 10 (23,439,075 to 23,442,377, forward strand). Ensembl gene ENSG00000165312.
Subcellular location (Human Protein Atlas): Cytosol
Pathways (Reactome):
Signal Transduction: Regulation of TNFR1 signaling; TNFR1-induced NF-kappa-B signaling pathway; TNFR1-induced proapoptotic signaling
Gene Ontology:
Molecular function: cysteine-type deubiquitinase activity; protein binding
Biological process: protein K63-linked deubiquitination; protein deubiquitination
Genetic constraint (gnomAD): Loss-of-function variants: 15 observed, 22.43 expected, observed/expected ratio (o/e) 0.67, 90% interval 0.45 to 1.03. The synonymous counts are far from expectation, so gnomAD's model fits this gene poorly and the ratio says little. Missense variants: 796 observed, 563.49 expected, observed/expected ratio (o/e) 1.41, 90% interval 1.33 to 1.5. Synonymous variants: 381 observed, 260.35 expected, observed/expected ratio (o/e) 1.46, 90% interval 1.35 to 1.59.
Homologues: Orthologues: chimpanzee OTUD1 (99% identical), macaque OTUD1 (97% identical), dog OTUD1 (90% identical), pig OTUD1 (89% identical), mouse Otud1 (75% identical), rat Otud1 (75% identical), zebrafish otud1 (39% identical), tropical clawed frog OTUD1 (34% identical), Drosophila melanogaster otu (8% identical), Drosophila melanogaster CG3251 (7% identical). Paralogues in human: OTUD5 (15% identical), OTUD6B (12% identical), OTUD4 (11% identical), OTUD6A (11% identical), OTUD3 (10% identical).
Diseases named in the same sentence as OTUD1 in open-access papers:
OTUD1 is named in the same sentence as 74 diseases in open-access papers, as found by Europe PMC text mining. Sharing a sentence is not in itself a finding about the gene and the disease. The quoted sentences say what the papers report.
breast carcinoma (15 papers, 2017 to 2025). "A study found that OTUD1 displays abnormally low expression in breast cancer, which is associated with cancer cell metastasis and lower survival." (PMID 41050073, 2025). "The authors also show that the loss of OTUD1 correlates with the poor prognosis of many tumor types, including glioblastoma, melanoma, and lung and breast cancers." (PMID 36829909, 2023). "From our screen, we have identified that loss of OTUD1 enables breast cancer cells to undergo EMT and gain cancer stem cell traits thereby driving metastatic spread to distant organs, such as bone and lung." (PMID 29235476, 2017). "We also elucidate the underlying mechanism and show that OTUD1 empowers SMAD7 to inhibit TGF-β signaling in breast cancer metastasis." (PMID 29235476, 2017). "Taken together, these analyses show that loss of OTUD1 strongly promotes breast cancer lung metastasis." (PMID 29235476, 2017). "We observed that some breast cancers express aberrantly low concentrations of OTUD1 as a result of OTUD1 gene loss or even gene deletion and that the loss of OTUD1 expression in patient correlates with a poor prognosis." (PMID 29235476, 2017). "Moreover, in both xenograft and orthotopic mouse cancer models, loss of OTUD1 expression is closely associated with breast cancer metastasis." (PMID 29235476, 2017). "Importantly, OTUD1 is lost in multiple types of human cancers and loss of OTUD1 increases metastasis in intracardial xenograft and orthotopic transplantation models, and correlates with poor prognosis among breast cancer patients." (PMID 29235476, 2017). "In this model, OTUD1 represses breast cancer metastasis by mitigating TGF-β activity and loss of OTUD1 in aggressive forms derives TGF-β signaling and metastasis." (PMID 37153745, 2023). "OUT domain-containing protein 1 (OTUD1) was found to inhibit breast cancer stem-cell traits and metastasis via deubiquitination of Smad7." (PMID 34059951, 2021). "The top hit, termed OTU domain-containing protein 1 (OTUD1), was found to inhibit breast cancer stem cell traits and metastasis." (PMID 29235476, 2017). "Here, the authors show that OTUD1 suppresses metastasis by antagonizing the TGF-β pathway via the deubiquitination of SMAD7, and its loss correlates with poor prognosis in breast cancer." (PMID 29235476, 2017). "We manipulated OTUD1 expression with either ectopic expression or knockdown strategies in the 4T1 murine breast cancer cell line and examined their ability to influence metastasis in vivo." (PMID 29235476, 2017). "Similarly, OUT domain-containing protein 1 (OTUD1) inhibits breast cancer metastasis by modulating Smad7 deubiquitylation, attenuating the TGF-β-induced oncogene response." (PMID 34059951, 2021). "Moreover, OTUD1 also increases MCL1 protein levels in the MCF7 breast cancer cell line and the Huh7 liver cancer cell line." (PMID 31467488, 2019). "Expression of OTUD1, a metastasis suppressor, is lost in the later stages of breast cancer." (PMID 29799477, 2018). "Expression of OTUD1 showed positive correlation with its gene copy number in breast cancer." (PMID 29235476, 2017). "Moreover, OTUD1 correlated with the SMAD7 expression in our breast cancer tissue microarray analysis, further corroborating that OTUD1 has an essential role in the control of SMAD7 stability and activity." (PMID 29235476, 2017). "Thus, OTUD1 represses breast cancer metastasis by mitigating TGF-β-induced pro-oncogenic responses via deubiquitination of SMAD7." (PMID 29235476, 2017).
breast carcinoma (continued). "We next examined the role of OTUD1 in breast cancer cell phenotypic behavior." (PMID 29235476, 2017). "Therefore, assessment of TGF-β1 signaling activity would be helpful in determining whether OTUD1-mediated regulation of TGF-β1 is specific to breast cancer or is also evident in cardiac remodeling but at the activity level." (PMID 37153745, 2023). "Furthermore, higher OTUD1 expression was significantly associated with low recurrence-free survival of HER2+ non-luminal subtype of breast cancer patients and EMT subtype of cervical cancer patients." (PMID 31467488, 2019). "Moreover, endogenous OTUD1 was found to interact with SMAD7 in breast cancer cells." (PMID 29235476, 2017). "In breast cancer, for instance, OTUB1, YOD1, OTUD5, OTULIN, TNFAIP3, and ZRANB1 drove chemoresistance, whereas OTUD1 and OTUD3 were sensitized to chemotherapy." (PMID 40469292, 2025). "For example, OTUD1 weakened the tumor response to TGF-β by removing ubiquitin from SMAD7, thereby inhibiting breast cancer proliferation." (PMID 40469292, 2025). "OTUD1 can deubiquitinate SMAD7 to enable SMURF2 binding and subsequent TβRI turnover on the cell surface to increase breast cancer metastasis." (PMID 38351029, 2024). "Among the ∼100 DUBs, several members, such as A20, USP43, OTUD1, OTUD3 and USP13, have been identified as key regulators in breast cancer." (PMID 37608493, 2023). "OTUD1 belongs to the OTU DUB family and plays important roles in immune responses and breast cancer by regulating different downstream substrates." (PMID 31467488, 2019). "Novel regulators of SMAD7, including OTU domain- containing protein 1 (OTUD1) and ubiquitin-specific protease 26 (USP26), attenuate TGF-β1-mediated aggressive phenotypes in breast cancer." (PMID 29799477, 2018). "Importantly, OTUD1 gene loss is also present in many other types of cancers, such as glioblastoma and lung cancers, indicating that the tumor suppressing role of OTUD1 may not be limited to breast cancer." (PMID 29235476, 2017). "However, OTUD1 and OTUD3 could curb the progression of breast cancer." (PMID 40469292, 2025). "In breast cancer cells, silencing OTUD1 promoted TGF-β-induced changes in EMT-marker expression, whereas ectopic expression of OTUD1-wt, but not OTUD1-CA, had the reverse effect." (PMID 29235476, 2017).
viral infection (9 papers, 2018 to 2026). "Among them, OTUD4 is induced in an IRF3/7-dependent manner, and OTUD1 increases the stability of MAVS during viral infection by directly removing the K48-linked ubiquitination of MAVS, thereby promoting RLR-mediated innate immune signals." (PMID 36505476, 2022). "Viral infection can cause upregulation of OTUD1, and OTUD1 as a DUB can attenuate the K6-linked ubiquitination of IRF3 to affect the DNA-binding ability of IRF3, thereby antagonizing the IRF3-mediated innate immune pathway." (PMID 36505476, 2022). "Based on this, we speculate that the significant findings of this study regarding OTUD1 and the NF-κB signaling pathway may be involved in the risk processes of all viral infections leading to stroke." (PMID 37695739, 2023). "Finally, we analyzed the effect of OTUD1 deficiency on viral infection." (PMID 29734366, 2018). "Studies have mentioned that OTUD1 plays a key role in modulating the immune response to viral infection." (PMID 35280681, 2022). "Here we report that RNA viruses specifically promote the deubiquitinase OTUD1 expression by NF-κB-dependent mechanisms at the early stage of viral infection." (PMID 29734366, 2018). "While it is possible that the OTUD1 peptide interaction with FP is mimicking the interaction of OTUD1 protein and FP during viral infection, it is also possible that the OTUD1 peptide may be mimicking some other natural ligand of FP." (PMID 41599331, 2026). "Previous studies have reported that after viral infections such as herpes simplex virus 1 (HSV-1) infection, OTUD1 is upregulated, and RNA viruses specifically promote the expression of the deubiquitinating enzyme OTUD1 through an NF-κB-dependent mechanism during the early stages of viral infection." (PMID 37695739, 2023). "Cellular OTUD1 proteins were upregulated by viral infection in a NF-κB-dependent manner." (PMID 33329486, 2020). "OTUD1 knockout mice show more resistance to virus infection and LPS stimulation." (PMID 32650621, 2020). "Finally, the deubiquitinase OTUD1 potently inhibits RLR pathway by utilizing Smurf1-MAVS/TRAF3/TRAF6 signaling at the early stage of viral infection." (PMID 29734366, 2018). "Therefore, we further observed the role of Smurf1 in OTUD1-mediated inhibitory effect on IFNs production during viral infection." (PMID 29734366, 2018). "Although the DUB OTUD1 has been shown to remove K63-linked polyubiquitination in autoimmune disease models, its involvement in early innate immune responses by reducing IRF3 K63 ubiquitination is minimal, primarily due to its upregulation during viral infection." (PMID 39761299, 2025). "Furthermore, OTUD1 inhibits type 1 IFN induction after virus infection through cleaving noncanonical K6-linked ubiquitination of IRF3." (PMID 32650621, 2020). "Moreover, we investigated the effect of the deubiquitinase activity of OTUD1 on viral infection." (PMID 29734366, 2018). "In vitro and in vivo experiments have shown that OTUD1 expression increases after viral infection, including HSV-1 infection, and OTUD1 knockout enhances the antiviral innate immune response." (PMID 37695739, 2023). "For instance, OTUD1 increases Smurf1 expression levels to promote degradation of the MAVS/TRAF3/TRAF6 signalosome and inhibit the innate immune response to viral infection." (PMID 35280681, 2022). "Conversely, OTUD1 overexpression decreased the levels of phosphorylated IRF3 and IRF3 homodimers during viral infection." (PMID 29734366, 2018). "Here, our results indicate that OTUD1 could utilize Smurf1 to downregulate MAVS/TRAF3/TRAF6 proteins and restrict IFNs production during viral infection." (PMID 29734366, 2018). "We next sought to determine how viral infection affects the levels of OTUD1, Smurf1 and MAVS/TRAF3/TRAF6, and whether the regulation signaling of OTUD1-Smurf1-MAVS/TRAF3/TRAF6 occurs during viral infection." (PMID 29734366, 2018).
viral infection (continued). "Furthermore, when viral infection was extended to 14 days, VSV loads in different organs from Otud1-/- mice were significantly reduced compared to their wild-type counterparts." (PMID 29734366, 2018).
cardiac hypertrophy (8 papers, 2023 to 2025). "Subsequently, we aimed to investigate the underlying molecular mechanism by which Otud1 regulates cardiac hypertrophy." (PMID 39309432, 2024). "In this study, via RNA sequencing, we revealed that Otud1 upregulated genes were associated with cardiac hypertrophy, Apoptosis, inflammatory responses, and protein process." (PMID 39309432, 2024). "Otud1 overexpression exacerbated cardiac hypertrophy and dysfunction, while its deficiency alleviated pathological cardiac hypertrophy." (PMID 39309432, 2024). "Together, these results show that OTUD1 deficiency protects against Ang II-induced myocardial hypertrophy and fibrosis." (PMID 37153745, 2023). "METTL3-mediated m6A modification of OTU Deubiquitinase 1 (OTUD1) exacerbates pressure overload-induced cardiac hypertrophy by deubiquitinating PGAM5." (PMID 41194259, 2025). "Echocardiography results, along with measurements of HW/BW, HW/TL, gross heart size, cardiomyocyte size and interstitial fibrosis, indicated that myeloid‐specific OTUD1 knockout abrogated ISO‐driven cardiac hypertrophy and fibrosis." (PMID 39118286, 2024). "The deubiquitinate enzyme activity of Otud1 is necessary for the role of the Otud1-Pgam5-Ask1 axis in the regulation of cardiac hypertrophy." (PMID 39309432, 2024). "To further investigate the involvement of Otud1 in the development of pathological cardiac hypertrophy in vivo, we utilized Otud1-CKO mice." (PMID 39309432, 2024). "This suggests the activation of Ask1-p38/JNK signaling pathways contributes to Otud1-induced cardiac hypertrophy." (PMID 39309432, 2024). "We demonstrated that Otud1 promoted cardiac hypertrophy by stabilizing Pgam5 protein expression, leading to elevated Ask1 phosphorylation." (PMID 39309432, 2024). "Nevertheless, there is still a gap in understanding the comprehensive regulatory network of OTUD1 in the context of controlling cardiac hypertrophy and remodeling." (PMID 39309432, 2024). "This study clarifies the participation and molecular mechanism of OTUD1 (OTU Deubiquitinase 1) in pathological cardiac hypertrophy." (PMID 39309432, 2024). "In terms of pathogenesis, Otud1 plays a crucial role in cardiac hypertrophy by targeting Pgam5, leading to the robust activation of the Ask1-p38/JNK signal pathway to accelerate cardiac hypertrophy." (PMID 39309432, 2024). "Our findings indicated that the deletion of the OTU domain did not exhibit any pro-hypertrophic effects on the NRVMs, suggesting the critical role of OTU domain in OTUD1-induced cardiac hypertrophy." (PMID 39309432, 2024). "Using OTUD1 knockout mice, we demonstrate that angiotensin II (Ang II)-mediated cardiac hypertrophy, fibrosis, and functional deficits are prevented when OTUD1 is deficient." (PMID 37153745, 2023). "Gross examination of heart tissues from mice suggested that OTUD1 knockout mice are protected against Ang II-induced cardiac hypertrophy." (PMID 37153745, 2023). "A total of six hub genes (TANC2, ADAMTS2, DYNLL1, MRC2, EGR1, and OTUD1) were considered cardiac hypertrophy and HF regulators." (PMID 37498303, 2023). "Histological analyses revealed that OTUD1 knockout mice are protected against TAC-induced cardiac hypertrophy and fibrosis." (PMID 37153745, 2023). "OTUD1 knockout mice, when challenged with the same Ang II regimen, showed suppressed myocardial hypertrophy and cardiac dysfunction." (PMID 37153745, 2023). "Comprehensive histological analyses showed that OTUD1 expression enhances Ang II-responses manifesting as cardiac hypertrophy and fibrosis." (PMID 37153745, 2023). "Six hub genes (TANC2, ADAMTS2, DYNLL1, MRC2, EGR1, and OTUD1) showed anomaly trend in cardiac hypertrophy." (PMID 37498303, 2023). "Building on our findings, we used the transverse aortic constriction (TAC) model of pressure overload-induced cardiac hypertrophy to study the role of OTUD1." (PMID 37153745, 2023). "We previously demonstrated that OTUD1 is involved in cardiac hypertrophy induced by Ang II." (PMID 40561034, 2025).
cardiac hypertrophy (continued). "Mechanistically, OTUD1 facilitated the procession of cardiac hypertrophy by directly binding to and deubiquitinating PGAM5 in a manner dependent on K63 ubiquitin chains, leading to enhanced ASK1 phosphorylation and p38/JNK MAPK signal pathway activation in cardiomyocytes." (PMID 39309432, 2024). "The protein expression of genes associated with cardiac hypertrophy (Anp and Myh7), was also found to be reduced in mice lacking Otud1." (PMID 39309432, 2024). "This study suggests that Otud1 inhibition may be a promising approach to alleviating cardiac hypertrophy." (PMID 39309432, 2024). "In summary, the absence of Otud1 successfully mitigated the development of pathological cardiac hypertrophy and cardiac fibrosis caused by TAC." (PMID 39309432, 2024). "Notably, our findings from echocardiography demonstrated that Ask1 inhibition effectively mitigated the exacerbating effects of Otud1 on cardiac hypertrophy." (PMID 39309432, 2024). "We speculated that OTUD1 might promote cardiac hypertrophy by activating MAPK signaling." (PMID 39309432, 2024). "Hence, focusing on the Otud1-Pgam5-Ask1 axis could potentially serve as a promising approach to address pathological cardiac hypertrophy." (PMID 39309432, 2024). "Hence, we speculated that OTUD1 could regulate the development of cardiac hypertrophy and heart failure." (PMID 39309432, 2024). "Our research advances the understanding of OTUD1's role in cardiac hypertrophy and remodeling by elucidating the specific molecular mechanism involving the METTL3-mediated m6A modification of OTUD1 mRNA." (PMID 39309432, 2024). "In summary, we reported for the first time that OTUD1 expression was upregulated due to m6A modification and that the OTUD1-PGAM5-ASK1 ternary complex is a critical cardiac hypertrophy promoter." (PMID 39309432, 2024). "In the cardiac hypertrophy dataset, GSE141910, we discovered that OTUD1 was the sole upregulated OTU member." (PMID 39309432, 2024). "To further validate role of METTL3 mediated OTUD1 RNA modification in cardiac hypertrophy in vivo, we used METTL3 inhibitor (STM2457) to treat AAV9-Otud1 mice." (PMID 39309432, 2024). "Cardiac hypertrophy and dysfunction were less frequent in Otud1-CKO mice during TAC treatment, while Otud1 overexpression worsened cardiac hypertrophy and remodeling." (PMID 39309432, 2024). "In conclusion, the current study identified upregulated OTUD1 in Ang II-challenged model of hypertensive cardiac dysfunction and showed that Ang II- and TAC-induced cardiac hypertrophy, fibrosis, and functional deficits are essentially prevented when OTUD1 is knocked out." (PMID 37153745, 2023).